MUC5AC (mucin 5AC, oligomeric mucus/gel-forming)
Diseases named in the same sentence as MUC5AC in open-access papers (continued):
Sharing a sentence is not in itself a finding about the gene and the disease.
asthma (continued). "In the largest genome-wide association study to date in moderate-to-severe asthma, Shrineet al. reported that variants in MUC5AC, GATA3 and KIAA1109 were associated with an increased susceptibility to developing moderate-to-severe asthma." (PMID 38609094, 2024). "It was reported that MUC5AC is overproduced in asthma, while MUC5B is related to lung homeostasis and defense." (PMID 38785919, 2024). "These mucous cells produce the mucin glycoprotein (MUC), the predominant form in the airways being MUC5AC; and the submucosal glands mainly produce MUC5B, with MUC5B being predominant under normal conditions and MUC5AC over-regulated in asthma." (PMID 37841931, 2023). "Autophagy in bronchial epithelial cells mediated collagen-I synthesis and MUC5AC expression as well as airway remodeling in asthma (Graphical Abstract)." (PMID 36803515, 2023). "The main component of mucus, MUC5AC, is typically fucosylated, and FUT2 exacerbates asthma through α-1,2-fucosylation of MUC5AC." (PMID 37256139, 2023). "Increased MUC5AC expression has been observed by a number of asthma studies and mucus plugs have been shown to contribute to airflow obstruction in the conducting airways." (PMID 36744026, 2023). "Consistently, immunohistochemistry analysis demonstrated that asthmatic MNKO mice had a remarkable increase in the number of cells expressing MUC5AC compared with asthmatic LC mice, suggesting improved goblet-cell metaplasia after asthma." (PMID 38030614, 2023). "Staining of lung tissues revealed that asthma-challenged Bmal1−/− mice displayed more severe bronchial epithelial cell hypertrophy, collagen deposition, and MUC5AC protein secretion compared with asthma-challenged Bmal1wt/wt mice." (PMID 36803515, 2023). "S100A8 and S100A9 can promote mucus hypersecretion typical of asthma in BECs, which is consistent with our previously published works documenting reduced MUC5AC post-BT along with IL-13+ cells in bronchial biopsies collected from a similar cohort." (PMID 37996952, 2023). "High concentrations of airway mucins—especially MUC5AC, which is elevated in patients with asthma—can interfere with the bactericidal activities of antimicrobial substances and can inhibit bacterial killing by neutrophils." (PMID 37759430, 2023). "Increased fucosylation of MUC5AC exacerbates airway inflammation and increases mucus viscoelasticity in asthma." (PMID 37256139, 2023). "The increased expression of MUC5AC in TH2 asthma was likely induced directly by the TH2 cytokine IL-13, which has been shown to increase MUC5AC in both human airway epithelial cells and mouse models." (PMID 37443808, 2023). "Previous reports have demonstrated abnormal elevation and accumulation of MUC5AC in the airway secretions of patients with pulmonary diseases such as asthma, COPD, and cystic fibrosis." (PMID 38004599, 2023). "In our asthma model, goblet cell hyperplasia, represented by an increased number of MUC5AC-positive goblet cells in the airway epithelium, was observed in OVA-challenged mice." (PMID 36831258, 2023). "In bronchial biopsies from children with chronic onset of asthma, some cells co-expressed mucus (MUC5AC and CEACAM5) and ciliated cell genes (FOXJ1 and PIFO), and were named as mucus ciliated cells." (PMID 36203653, 2022). "In the next step, the protein levels of Fn1 and Muc5ac in healthy, asthmatic, and asthma-driven fibrotic lungs were evaluated by IHC staining." (PMID 35625754, 2022). "In contrast to type 2 high asthma, the ratio of MUC5AC to MUC5B protein observed in our study was approximately 0.8 to 1.0." (PMID 35239513, 2022). "The transition of increased Muc5ac transcription in mucus-secreting cells was similar to the IL13-induced metaplastic process in human asthma airway epithelial cells." (PMID 35869072, 2022). "We employed ovalbumin (OVA)-sensitized mice to model of asthma and exposed them to type IV collagen to verify the reducing effect of MUC5AC in vivo." (PMID 36188610, 2022).
asthma (continued). "In patients with type 2-high asthma, an increased production of MUC5AC is correlated with mucus hypersecretion, airflow obstruction, and airway hyper-responsiveness." (PMID 36012669, 2022). "MUC5AC expressed as the percentage of airway epithelium staining was elevated in asthma compared with healthy controls (p < 0.0001), with similar increases in all asthma subgroups." (PMID 35579040, 2022). "In contrast, the remodelling features of airway smooth muscle mass and MUC5AC expression were increased in all asthma groups compared with health, but similar across asthma subgroups." (PMID 35579040, 2022). "On the other hand, MUC5AC levels in asthma disproportionately and consistently increase in response to cigarette smoke and allergens." (PMID 36012669, 2022). "These were in loci previously associated with asthma exacerbations (GSDMB, RAD50, HLA‐DQB1, ADAM33, VDR, and CDHR3) or moderate‐to‐severe asthma (IKZF3, TSLP, MUC5AC, C11orf30, SMAD3, and WDR36)." (PMID 35754128, 2022). "MUC5B is generally considered to be the homeostatic mucin, whereas MUC5AC is more inflammatory, being strongly induced by T2 inflammation as well as other asthma-related environmental challenges, including particulate matter and cigarette smoke." (PMID 35347136, 2022). "MUC5AC expression was increased in the airway epithelium and to a similar extent across the asthma cohorts." (PMID 35579040, 2022). "Our data confirmed that the mRNA expression of proinflammatory cytokines was significantly increased in the lung tissue of OVA + WPM mice compared to OVA-induced asthma mice, and the expression of MUC5AC also showed a slight tendency to increase." (PMID 35837279, 2022). "We report airway cis-genetic risk variants for MUC5AC and FOXA3, alleles of which are associated with both increased expression of these genes and asthma risk." (PMID 35347136, 2022). "MUC5AC is a well-known mucus protein that is produced by airway surface epithelium and involved in the development of asthma." (PMID 36046596, 2022). "Clinical studies have shown that MUC5AC is the most abundant protein in the mucus of patients with asthma." (PMID 36699060, 2022). "The mucus in IL-13-treated mice and in patients with asthma contains a high proportion of the mucin Muc5AC." (PMID 35997279, 2022). "Intracellular stores of MUC5AC, a major airway mucin involved in asthma, were rapidly depleted, likely to trap viruses." (PMID 35353667, 2022). "Venn diagram analysis revealed 24 genes common for both disorders, including asthma-specific key nodes Timp1, Cyp2e1, and Muc5ac." (PMID 35625754, 2022). "Increased Gal-3 in mice with TIMPKO, murine asthma model is associated with decreased MUC5AC and MUC5B levels, while inhibition of Gal-3 results in increased MUC5AC and MUC5B in a lung epithelial cell line." (PMID 34221020, 2021). "The polymeric mucins, Muc5ac and Muc5b are primarily responsible for mucus production in mouse models of asthma." (PMID 35386975, 2021). "This layer contributes to biological defense by eliminating irritants, but excessive MUC5AC secretion by the airway epithelial cells exacerbates asthma." (PMID 34504957, 2021). "So far, many reports on the regulation of MUC5AC production have been made as a method for asthma treatment." (PMID 34504957, 2021). "Previous studies found that the assembly of cilia is remarkably decreased but the secretion of mucins (encoded by MUC5AC and MUC5B) is increased in COPD, asthma, IPF, and cystic fibrosis." (PMID 34149803, 2021). "The agonists of ACh are related to the modulation of a specific type of mucin known as MUC5AC, the main mucin glycoprotein responsible for mucus viscoelasticity in asthma." (PMID 34055794, 2021). "Controlling MUC5AC production is an important aspect of asthma treatment; therefore, elucidating the regulatory mechanisms underlying MUC5AC secretion will lead to the development of novel therapies." (PMID 34504957, 2021).
asthma (continued). "Cockroach allergen-induced Muc5ac expression and aryl hydrocarbon receptor (AhR) signaling activation was examined in the human bronchial epithelial cells (HBECs) and mouse model of asthma." (PMID 34868022, 2021). "This pathway preferentially induces the mucin glycoprotein MUC5AC in vitro, recapitulating its preferential induction of MUC5AC in airway epithelial brushings from humans with T2-high asthma." (PMID 33682796, 2021). "Of interest, IL-1β signaling has been shown to be critical in inducing neutrophil chemotactic factors, IL-33, and Muc5ac expression at viral-induced asthma exacerbation." (PMID 34868022, 2021). "Recently, this MUC5AC signal has been identified as potentially more relevant to adult onset asthma, a phenotype that shares less overlap with atopic comorbidities than childhood onset asthma." (PMID 35386986, 2021). "We sought to investigate the immunological pathway that controls Muc5ac expression and allergic airway inflammation in asthma." (PMID 34868022, 2021). "Gal-3 modulates the IL-17 axis, which regulates mucin gene expression of MUC5AC, leading to mucus hypersecretion and persistent airway inflammation in asthma." (PMID 34221020, 2021). "The ratio between MUC5B and MUC5AC changes dramatically in asthma because MUC5AC expression and protein production are substantially upregulated in asthmatic patients." (PMID 32411147, 2020). "In contrast, LOL treatment significantly suppressed the phosphorylation of MAPKs/AP-1, p65NF-κB, and expression of MUC5AC in the lung tissues compared with the OVA-challenged asthma model." (PMID 32605045, 2020). "In mice, excess mucus production is a cardinal feature of asthma that is regulated by 2 polymeric mucins: Muc5ac and Muc5b." (PMID 32477356, 2020). "For examples, significant DEGs in our list are involved biomarkers of Th2 response (POSTN), inflammation (NOS2, ALOX15) and mucus production (MUC5AC) corroborated with a previous metanalysis of airway gene expression in asthma." (PMID 32900903, 2020). "It turned out that the mRNA expressions of several inflammatory factors, such as tumor necrosis factor (TNF), Muc5ac, IL-4, IL-13, and IL-12b were significantly upregulated in asthma group compared with control and diacerein groups." (PMID 33013396, 2020). "In this study, LOL treatment suppressed the activation of MAPKs/AP-1 and p65NF-κB, and inhibited expression of MUC5AC in OVA-challenged asthma mice." (PMID 32605045, 2020). "Our results suggest that type IV collagen downregulates MUC5AC secretion in three-dimensional cultured human primary airway epithelial cells derived from patients with asthma." (PMID 31737795, 2019). "The T helper 2 cytokine IL-13 is thought to be the main inducer of goblet cell hyperplasia and MUC5AC production in murine models of asthma, through activation of STAT6." (PMID 30764493, 2019). "Then, several studies confirmed that MUC5AC is the major component of mucus in the airway in asthma in both human and animals." (PMID 31073274, 2019). "The three-dimensional cultured primary airway epithelial cells from patients with asthma showed constitutive MUC5AC secretion into the culture medium." (PMID 31737795, 2019). "Mucin 5AC (MUC5AC) hypersecretion induces airway narrowing in patients with asthma, which leads to breathing problems." (PMID 31737795, 2019). "MUC5AC expression is raised in ovalbumin murine models of asthma, and is increased further by RSV infection." (PMID 30764493, 2019). "Although considerable changes in ECM proteins in the airway epithelia have been observed in patients with asthma, the relationship between these changes and MUC5AC secretion remained unclear." (PMID 31737795, 2019). "MUC5AC is mainly expressed in the epithelium, and significantly increased levels of MUC5AC are required for airflow obstruction in murine asthma models." (PMID 31692453, 2019).
asthma (continued). "In our study, MUC5AC and MUC5B mRNA levels were significantly increased in asthma mice compared to those in control mice, and Baicalein treatment induced substantial decreases in MUC5AC and MUC5B mRNA expression levels." (PMID 31692453, 2019). "Taken together, these data suggest that TGF-β3 signaling is involved in ROS production, autophagy activation, and MUC5AC expression in the asthma mice models." (PMID 32082074, 2019). "In this study, ECM proteins regulated MUC5AC secretion in human primary airway epithelial cells which were derived from patients with asthma and in human lung epithelial cell line NCI–H292." (PMID 31737795, 2019). "Several in vitro and in vivo studies have described the regulation of MUC5AC expression in human primary airway epithelial cells as a potential therapeutic target in asthma." (PMID 31737795, 2019). "To date, more than 20 human mucin genes have been identified, and the principal airway gel-forming mucins in asthma are MUC5AC and MUC5B." (PMID 31692453, 2019). "To our knowledge, we provide the first evidence on the role of caveolin-1/VEGFR2 on VEGF-induced RhoA activation and MUC5AC upregulation in bronchial epithelial cells, suggesting an effective therapeutic target in inflammatory diseases such as asthma." (PMID 31831011, 2019). "Mucus hyperproduction and increased MUC5AC expression are characteristic features of asthma and COPD." (PMID 30654796, 2019). "We identified three novel genome-wide significant genetic associations that imply MUC5AC, GATA3, and KIAA1109 have an association with susceptibility to the development of moderate-to-severe asthma." (PMID 30552067, 2019). "Immunofluorescence staining revealed reduced MUC5AC expression in anti-TGF-β3 Ab-treated asthma mice models." (PMID 32082074, 2019). "MUC5AC hypersecretion owing to increased airway mucus is a characteristic feature in patients with asthma." (PMID 31737795, 2019). "These consequences suggested that oxidant stress has a vital role in triggering autophagic activity and subsequently MUC5AC expression in the asthma mice models." (PMID 32082074, 2019). "Mucins are glycoproteins that are mainly responsible for the viscoelastic property of mucus, and MUC5AC is a major mucin glycoprotein that is overproduced in asthma." (PMID 31831011, 2019). "Since bronchial contraction and MUC5AC hypersecretion are two important factors that induce airway narrowing, reduction in MUC5AC secretion is important in treating asthma." (PMID 31737795, 2019). "We investigated the regulation of MUC5AC secretion by extracellular matrix (ECM) proteins in human primary airway epithelial cells from patients with asthma." (PMID 31737795, 2019). "Particularly, MUC5AC is well-kwon as a main component of airway mucus and associated with airflow limitation and AHR in patients with asthma." (PMID 30135657, 2018). "In asthma, it is known that Muc5ac-rich mucus impairs the cilia-driven transport by epithelial tethering without defects in the cilia function." (PMID 29614747, 2018). "In asthma, MUC5AC levels are significantly increased, whereas MUC5B levels remain stable or decrease, compared with healthy lungs." (PMID 30154090, 2018). "A similar negative correlation between AQP5 and MUC5AC was also found in the lung tissue of the asthma model of mouse; the MUC5AC expression was significantly increased when AQP5 expression was downregulated by RNA interference." (PMID 28630635, 2017). "MUC5AC is a major mucin protein secreted from the airway surface epithelium and played important role in asthma." (PMID 29311942, 2017). "In asthma as in health, MUC5AC is produced in goblet cells from the surface epithelium, while MUC5B is largely produced in the submucosal glands." (PMID 29186064, 2017). "In children with asthma, we observed an increased MUC5AC concentration, particularly in those with acute disease." (PMID 28716644, 2017).
asthma (continued). "Concentration of MUC5AC showed considerable variation among the three groups studied, with geometric means of 7.6, 22.4, and 44.7 μg/mL in the control subject, stable asthma, and acute asthma groups, respectively." (PMID 28716644, 2017). "The proportion of sputum eosinophils was significantly greater in children with asthma than in control subjects, and we found that total mucin, MUC5AC, and MUC5B were correlated with sputum eosinophils in children with stable disease." (PMID 28716644, 2017). "Sputum MUC5AC concentrations were 7.6 μg/mL in control subjects, 22.4 μg/mL in those with stable asthma (P = .17), and 44.7 μg/mL in those with acute asthma (P < .05)." (PMID 28716644, 2017). "We found a similar relationship between eosinophils and concentrations of MUC5B and MUC5AC in stable asthma." (PMID 28716644, 2017). "A recent study has suggested that type 2 inflammation is necessary but not sufficient for allergic asthma, and that the airway epithelium is more responsive to type 2 inflammation in people with asthma as measured by MUC5AC." (PMID 29186064, 2017). "We found that MUC5AC concentration was increased in children with asthma compared with that in control subjects, particularly in children with acute asthma, resulting in a significant change in the MUC5B:MUC5AC ratio." (PMID 28716644, 2017). "MUC5AC is recognized as the most common mucin gene whose expression is markedly increased in asthma and is mediated by M3R in goblet cells." (PMID 29213218, 2017). "In bronchial epithelial cells cultured from asthma patients, there is a reported increase in mucin production, including MUC5AC." (PMID 27655795, 2016). "MUC5AC immunostaining was also increased in asthma compared to health (P = 0.030), again driven by severe asthma (P = 0.034 for severe asthma compared to healthy controls)." (PMID 26689552, 2015). "As mucus hypersecretion relates to HRV-induced asthma exacerbations, MUC5AC protein expression was examined in ALI cultures after RV-A16 infection compared to vehicle treatment by immunofluorescence." (PMID 25706956, 2015). "Consistent with this, the ALI culture derived from donor 23 had a higher amount of MUC5AC expression before viral infection, but donor 11 had a similar expression level to other non-asthma donors." (PMID 25706956, 2015). "Our present findings reveal that mCLCA3 antibody treatment of asthmatic mice effectively ameliorated the symptoms of asthma, such as airway inflammation and muc5ac secretion." (PMID 24349268, 2013). "The regulation of muc5ac expression in airway epithelial cells is a critical target for asthma treatment." (PMID 24349268, 2013). "IL-13 stimulation can induce CLCA1 and MUC5AC expression in normal human bronchial epithelial cells and murine asthma models." (PMID 22731784, 2012). "In murine asthma model, airway MUC5AC gene was over-expressed after 24 hour sensitization of ovalbumin." (PMID 21134294, 2010). "Our results suggest that liquiritin may help mitigate asthma symptoms by inhibiting both intracellular and secreted levels of MUC5AC and MUC5B through suppression of ERK and p38 signaling." (PMID 40869396, 2025). "Whereas MUC5AC and mucin 5B secretion are reduced in an asthma mouse model with TRPV1 knockout." (PMID 39958344, 2025). "Asthma granulocytic mucus plugs are therefore characterized by high number of granulocytes that release extracellular traps and by a mucin profile that includes both MUC5AC and MUC5B mucins." (PMID 40091838, 2025). "Additionally, CME reduced the expression of MUC5AC, a protein implicated in airway obstruction and respiratory dysfunction in diseases such as COPD and asthma." (PMID 40081908, 2025). "Beyond airway inflammation, the upregulation of MUC5AC highlights its specific role in asthma." (PMID 40309741, 2025). "Together, these findings support that AAV6 may be used as an inhaled gene therapy to suppress MUC5AC overexpression and restore normal airway clearance function in asthma." (PMID 40849510, 2025).